IL6 (interleukin 6)
Diseases named in the same sentence as IL6 in open-access papers (continued):
Sharing a sentence is not in itself a finding about the gene and the disease.
neuropathy (continued). "LPS-RSU restored the balance between algesic IL-18 and analgesic IL-18BP, additionally increasing the IL-6 level, which in neuropathy is known to have analgesic properties." (PMID 29656686, 2018). "Patients in the metformin group were significantly younger, and had a slightly higher eGFR-MDRD, less neuropathy, and lower serum IL-6." (PMID 28202017, 2017). "The nociceptive factors that undergo the strongest activation during neuropathy include iNOS, IL-1beta, IL-18 and IL-6." (PMID 26426693, 2015). "Increased IL-6 serum levels have been detected in patients with neuropathy, malignant tumors, musculoskeletal disorders, burn injury or autoimmune and chronic inflammatory conditions like RA." (PMID 21951917, 2011). "Amantadine was able to significantly reduce (p < 0.0001) the expression of Il-6 in the spinal cord of rats with chemotherapy-induced neuropathy, which is demonstrated by the statistical difference in relation to the positive control group; its highest effect was observed at the dose of 50 mg/kg." (PMID 38998053, 2024). "An experimental study conducted on streptozotocin-induced diabetic rats revealed a close association between the elevation of inflammatory cytokines in brain tissues, such as interleukin-6 and tumor necrosis factor alpha, and the initiation and progression of neuropathy." (PMID 38370902, 2023). "Besides TNF-α, IL-6 (interleukin-6) production undergoes an increase in diabetic patients with neuropathy." (PMID 37629665, 2023). "Accumulating evidence implicates that P2x4 potentiates P2x7-dependent release of proinflammatory cytokines including IL-1β, IL-6 and Tnfα in both central and peripheral nervous systems, leading to neuroinflammation, which contributes to induce neuropathy and abnormal nociception." (PMID 35332157, 2022). "The relevance of the CMT neuropathy score (CMTNS) can be further improved by objective measurements in humans in addition to the electrophysiological recording of the compound muscle action potential (CMAP) to also include plasma levels of IL-6 and MRI." (PMID 35806409, 2022). "Interleukin-6 plays a crucial role in the development and progression of neuropathy, and the increase in the concentration of IL-6 with the severity of painful neuropathy suggests that IL-6 may mediate the development of painful DPN." (PMID 35155045, 2022). "Our findings demonstrate that IL-6 plays a pivotal role in the pathophysiology of paclitaxel-induced neuropathy per se and that pharmacological or genetic interference with this signaling pathway prevents the development of this potentially debilitating adverse effect." (PMID 31969555, 2020). "Furthermore, pretreatment with an IL-6-neutralizing antibody resulted in the prevention of paclitaxel-induced neuropathy in C57BL/6 mice." (PMID 31969555, 2020). "In this cohort, measured Il-6 levels correlated with the severity of neuropathy." (PMID 31969555, 2020). "A small-sized multicentre phase II trial reported a shift in the T helper type 1 (Th1)/ T helper type 2 (Th2) cytokine balance towards Th2 dominance with elevated levels of interleukin-6 (IL-6) in the peripheral blood of patients who developed a painful neuropathy during treatment with bortezomib." (PMID 32906684, 2020). "Moreover, a highly specific TLR4 antagonist modulated the interleukin expression levels in DRG, restoring the balance between pronociceptive IL-18 and analgesic IL-18BP, and increased the IL-6 level, which in neuropathy is known to have analgesic properties." (PMID 29656686, 2018). "It has been reported that IL-6 is elevated in diabetic patients with neuropathy." (PMID 28841856, 2017). "Interestingly, similar results were obtained with low-dose IL-6 treatment on chemotherapy-induced neuropathy models, highlighting that in addition to metabolic targets, IL-6 also exerts neuroprotective effects on nerve cells outside of the diabetic milieu." (PMID 28512447, 2017).
neuropathy (continued). "Another cytokine analyzed in present study is IL-6, which is considered to be a pleiotropic cytokine with pronociceptive and antinociceptive properties, but its role in neuropathy remains unclear." (PMID 26090236, 2015). "IL-10 inhibits the release of IL-1β and IL-6 and plays role in neuropathy." (PMID 26090236, 2015). "All treatments were able to down-regulate the expression of TNF-α and IL-6, up-regulate the expression of TGF-β, rapidly improve hyperalgesia, grip strength, motor coordination, and nerve conduction velocity in rats with streptozotocin (STZ)-induced neuropathy, and improve neuropathy caused by T1D." (PMID 37175774, 2023). "Moreover, the levels of IL-6 in CSF correlated with the severity of neuropathy, thus indicating that the inflammation at the nerve roots might be the cause or consequence of the neurodegeneration." (PMID 36860843, 2023). "The glucose fermentation of C. acnes or its fermentation metabolite butyric acid and its derivative BA-NH-NH-BA may inhibit HDAC to activate AcH3K9 in keratinocytes, successfully ameliorating the CaP-induced pruritic inflammation and neuropathy by inhibition of IL-6 in the skin and p-ERK 1/2 in DRG." (PMID 31979095, 2020). "In neuropathies, immune-cell accumulation leads to the release of inflammatory cytokines; serum TNF and IL-6 expression increase during this process." (PMID 41462977, 2025). "Other proteins that have been implicated in the pathogenesis of taxane and vinca alkaloid induced neuropathy include protein kinase C (PKC), interleukin 6 (IL6), and the components of the Wnt signaling pathway." (PMID 40595283, 2025). "The anti-hyperalgesic effect of hesperidin in the CCI neuropathy model in rats is attributed to the inhibition of pro-inflammatory cytokines TNF-α and IL-6." (PMID 40718454, 2025). "Sciatic nerve injury in a rodent model of neuropathy upregulates P2X4R expression in spinal microglia leading to increased production of IL-1β, TNFα and IL-6." (PMID 37166584, 2023). "Mice with neuropathy (14th day after PSNL) were treated with crotalphine and one hour later the ipsilateral spinal cord was collected for IL-6 quantification." (PMID 36232883, 2022). "Microglia are activated by neurotransmitters secreted from the terminals of presynaptic neurons in the dorsal horn of the spinal cord, and neuropathy is induced by the secretion of various inflammatory factors (TNF-α, IL-1β, and IL-6)." (PMID 34073390, 2021). "We found that IL6, TNF, CXCL8, IL1B and ERK1/2 were the top genes in terms of the number of connections in platinum-induced neuropathy, suggesting either direct or indirect interactions with nervous tissue leading to CIPN after exposure to platinum compounds." (PMID 26269716, 2015). "Our previously study demonstrated that minocycline diminished the level of proinflammatory factors, such as IL-6, IL-18, and MMP-9, during neuropathy and enhanced morphine effectiveness." (PMID 26426693, 2015). "According to our results, the pro-inflammatory marker IL-6 is highly correlated with the severity of pain rather than the severity of neuropathy score." (PMID 35155045, 2022). "We found similar results where IL-6 levels were positively correlated with painful DPN rather than neuropathy severity according to TCS." (PMID 35155045, 2022). "The pathogenesis of UP may involve inflammatory states, such as increased levels of pro-inflammatory cytokines (IL-6, IL-2, and TNF-α), immune changes, and neuropathy." (PMID 37675019, 2022). "Particularly, increased levels of IL-1β, IL-6 and TNF-α in ALS patients compared to controls or patients with other neuropathies have been reported, suggesting that the modulation of these inflammatory mediators may ameliorate the course of the disease." (PMID 36362341, 2022).
neuropathy (continued). "However, IL-6 in T2D patients with DPN was significantly higher than in patients with T2D without neuropathy." (PMID 35155045, 2022). "However, in the context of paclitaxel-induced neuropathy it was shown that spinal IL-6 synthesis is not increased as measured by rt-PCR55." (PMID 31969555, 2020). "The untreated group without neuropathy showed higher concentrations of TNF-α, Chitinase3, IL-6, and IL-10 than the other groups." (PMID 34640602, 2021). "Here, IL-6 level was not increased by CCI, and thus IL-6 certainly did not act as proinflammatory cytokine at least in the peripheral nerve undergoing neuropathy." (PMID 30622591, 2018). "As the primary aim of this study was to evaluate the predictive value of sCD14, IL-6, and PCT, the lack of a neuropathy score does not influence our results." (PMID 24948983, 2014). "However, our data points to an essential role of IL-6 in the pathogenesis of CIN as IL-6–/– mice treated with PTX did not develop typical behavioral, electrophysiological or histological signs of neuropathy at all." (PMID 31969555, 2020).
lupus nephritis (83 papers, 2010 to 2025). Glomerulonephritis in the context of systemic lupus erythematosus. "Animal experiments have also shown that IL-6 deficiency can effectively delay the occurrence of lupus nephritis, improve kidney function, and prolong the survival of SLE mice." (PMID 37049889, 2023). "Other researches on adult SLE have shown that high level of IL-6 were associated with increased disease activity and ds-DNA titers, meanwhile IL-6 was significantly elevated in the serum of patients with lupus nephritis, our study produced similar results." (PMID 33882880, 2021). "In a Lyn-deficient mouse, which has elevated IL-6 and lupus nephritis symptoms, treatment with the IL-6 trans signalling inhibitor sgp130Fc attenuated the disease and improved renal function." (PMID 30871285, 2019). "Several studies on experimental models of SLE had shown an association of IL-6 with progression of lupus nephritis." (PMID 25548434, 2014). "IL-6 is a pleiotropic cytokine with both pro-inflammatory and anti-inflammatory properties and has been implicated in the pathogenesis of lupus nephritis." (PMID 23642011, 2013). "Deficiency of IL-6 in MRL-Fas lpr mice delay lupus nephritis." (PMID 28587079, 2017). "An association of raised IL-6 levels with lupus nephritis has been reported earlier." (PMID 25548434, 2014). "IL-6 is also associated with lupus nephritis and joint damage." (PMID 23702100, 2013). "IL-6-deficient Mrl/lpr mice show a delayed onset of lupus nephritis and prolonged survival." (PMID 23702100, 2013). "IL-4 was elevated in SLE patients with nephritis, correlating with IL-6, IL-10, sCD40L, and IL-8, suggesting B cell involvement in lupus nephritis." (PMID 39379404, 2024). "Along these lines, urinary samples of patients with lupus nephritis contained significant IL-6 activity, and IL-6 mRNA was expressed in the glomeruli of patients." (PMID 37189804, 2023). "In support of this, patients with lupus nephritis had indeed increased urinary IL-6 concentrations compared to patients with normal kidney function." (PMID 37189804, 2023). "In this sense, urinary IL-6 levels in 29 patients with active class IV lupus nephritis were significantly higher than in patients with other classes of lupus nephritis." (PMID 37762312, 2023). "Mesangial cell proliferation can be triggered by infections due to increase proinflammatory cytokines such as Il-6, and IL-8 immune complexes (IgA disease and lupus nephritis." (PMID 36374911, 2022). "Specifically, in lupus nephritis, macrophages and monocytes invade the cells in the kidney and produce IL-6." (PMID 36298107, 2022). "Immune complexes depositing in the thyroid lead to immune cell infiltration (T and B lymphocytes) and cytokine release (INF‐γ, IL‐6, IL‐12, IL‐21, and IL‐17), like Lupus nephritis, which will exacerbate thyroid tissue damage." (PMID 34850456, 2022). "We also demonstrated the importance of proinflammatory mediators in kidney fibrosis and the contribution of IL-6 in inducing fibrogenesis in lupus nephritis." (PMID 35571122, 2022). "Given that proteinuria is one of the key features of lupus nephritis, our finding of an increase in urinary protein levels following IL-6 increases after 36–48 h confirms, in principle, results from laboratory studies." (PMID 34975831, 2021). "A recent study showed that monotherapy with TAC significantly diminished proteinuria and Toll-like receptor-7 expression and induced the suppression of IL-6 production in lupus nephritis mice." (PMID 33865397, 2021). "Lupus nephritis patients have increased level of urinary IL-6 and expression of IL-6 was increased in the glomerular tissues." (PMID 34733276, 2021). "For example, in an experimental study on IL-6-knockout mice, Cash and colleagues observed delayed lupus nephritis with a marked reduction of proteinuria compared to IL-6-intact control mice." (PMID 34975831, 2021).
lupus nephritis (continued). "In a recent review, IL-6 was suggested as an important mediator in lupus nephritis, and urinary IL-6 has also been suggested as a marker for it." (PMID 34768756, 2021). "Lupus nephritis patients have significantly elevated levels of IL-6, and IL-6 can be used as a sensitive biomarker for disease activity and a predictor of remission in these patients." (PMID 34425760, 2021). "In our previous study we found that Fli-1 directly regulated IL-6 expression and promoted the progression of lupus nephritis." (PMID 32183259, 2020). "Evidence from a mouse model of lupus nephritis suggests that the increase in IL-6 is the result of a decrease in expression of a micro-RNA that regulates IL-6." (PMID 30871285, 2019). "This is thought to contribute to the pathogenesis of lupus nephritis since blockade of IL-6 or the IL-6 receptor ameliorates kidney disease in lupus-prone mice." (PMID 30333818, 2018). "Urinary IL-6 correlates with titers of anti-dsDNA antibodies and decreases following treatment in patients with lupus nephritis." (PMID 29422675, 2018). "A recent study revealed that B cells are major source of pro-inflammatory IL-6 and a key driver of lupus nephritis." (PMID 29441062, 2018). "Apart from the obvious proinflammatory activities attributed to IL-17, increased production of total IgG, anti-dsDNA IgG, and IL-6 by peripheral blood mononuclear cells of patients with lupus nephritis was observed when cultured with IL-17." (PMID 28545118, 2017). "A 2015 study determined cutoffs of cytokines IL-17 and IL-6 to diagnose lupus nephritis in patients with SLE." (PMID 28487810, 2017). "Serum levels of Th1 cytokines (IFN-γ, IL-18, and IL-12p70) and Th17 cytokines (IL-17A and IL-6) were significantly elevated in lupus nephritis-IV when compared with healthy control." (PMID 27738386, 2016). "Th1 and Th17 cytokines (IL-18, IFN-γ, IL-12p70, IL-6, and IL-17A) were considerably expressed in the serum of lupus nephritis IV patients in comparison to the healthy control." (PMID 27738386, 2016). "In lupus nephritis, IL-6 deposition is localized to mesangial cells and podocytes and is also present alongside immune deposits in the glomerulus." (PMID 26441980, 2015). "Up to 70% of patients with lupus nephritis have discernible immune aggregates and IL-6 expression along the tubular basement membrane." (PMID 24171032, 2013). "Serum and urinary IL-6 levels are increased in patients with lupus nephritis, especially in those with diffuse proliferative lupus nephritis, and correlate with nephritic flares." (PMID 24171032, 2013). "Further analysis of inflammatory markers revealed that SAP treatment notably decreased systemic and local inflammatory cytokine levels of TNF-α, IL-1β, IL-6, IL-12, and MCP-1, which were closely associated with the severity of lupus nephritis." (PMID 21799927, 2011). "We wondered if upregulation of WDFY1 could be induced by the IL-6-driven upregulation of Sp1 expression in the kidney of lupus nephritis mice." (PMID 40497974, 2025). "While it has been proposed that the presence of Proteobacteria in gut could potentially play a role in the pathogenesis of lupus nephritis by promoting IL-6 production." (PMID 40616747, 2025). "IL-6 facilitates the differentiation of B cells into plasma cells that produce autoantibodies, with elevated IL-6 levels correlating with disease activity and severity, particularly in lupus nephritis." (PMID 39329714, 2024). "IL-6 played an important role in the progression of lupus nephritis." (PMID 37322353, 2023). "IL-6 expression in renal tissue is rising in lupus nephritis patients." (PMID 37049889, 2023). "IL-6 is overexpressed in kidney, and through its proinflammatory actions, it plays a crucial role in membrane-proliferative glomerulonephritis, IgA nephritis, lupus nephritis, diabetic nephropathy, acute kidney injury, chronic kidney disease." (PMID 34205600, 2021).